TLR4 (toll like receptor 4)
Diseases named in the same sentence as TLR4 in open-access papers (continued):
Sharing a sentence is not in itself a finding about the gene and the disease.
Cirrhosis (56 papers, 2010 to 2026). A chronic disorder of the liver in which liver tissue becomes scarred and is partially replaced by regenerative nodules and fibrotic tissue resulting in loss of liver function. "In clinically relevant rodent models of hyperammonemia (genetic ornithine transcarbamylase deficiency and bile duct ligation–induced cirrhosis), TLR4 inhibition reduced circulating ammonia." (PMID 40053595, 2025). "This process activates Toll-like receptor 4 and upregulates the NF-κB signaling pathway, further promoting the risk of cirrhosis." (PMID 41202080, 2025). "These suggest that cirrhosis can cause a decrease in miR-532-3p by causing inflammation in vivo and activating TLR4, leading to the development of sarcopenia." (PMID 37881635, 2023). "TLR2 is upregulated only after incubation with plasma from patients with alcohol-associated cirrhosis, while TLR4 is upregulated in neutrophils treated with plasma from patients with both alcohol-associated and viral cirrhosis." (PMID 37822786, 2023). "Increased sensitivity to endotoxins in cirrhosis is associated with upregulation of hepatic TLR4, which explains susceptibility to development of ACLF whereas acute liver failure is likely due to direct hepatoxicity." (PMID 31942020, 2020). "TLR-4 has been identified as a factor associated with a high risk of developing cirrhosis in patients with chronic hepatitis C. Moreover, TLR-4 activation has been associated with the progression of other chronic liver diseases, such as AIH, PBC and PSC." (PMID 32756323, 2020). "TLR4 was identified as one of seven genes associated with increased risk of developing cirrhosis in patients with chronic hepatitis C." (PMID 20964825, 2010). "In humans, single nucleotide polymorphisms of the TLR4 gene have an effect on its signal transduction and on associated risks of specific diseases, including cirrhosis." (PMID 20964825, 2010). "In addition to inhibiting RIPK1 and RIPK3, inhibition of the TLR4 pathway by TAK-242 or TLR4 deficiency was found to significantly reduce circulating ammonia levels, which was validated in clinically relevant models of hyperammonemia due to cirrhosis or UCD." (PMID 40053595, 2025). "In cirrhosis, chronic stimulation by pathogen-associated and damage-associated signals sustains the TLR4–NF-κB pathway, and STAT3-mediated feedback progressively biases these cells toward tolerance, leaving T cells less responsive to subsequent checkpoint blockade." (PMID 41488615, 2025). "Because persistent TLR4 signaling sustains tolerogenic macrophage states in cirrhosis, TLR4 inhibition reduces immunosuppressive mediators and improves antitumor responses, making it a plausible partner in combination regimens." (PMID 41488615, 2025). "Studies have shown that TLR4 expression increases with advancing cirrhosis and promotes HCC, but it is relatively low in HCC compared to adjacent normal tissue, indicating its close relationship with HCC." (PMID 39824843, 2025). "Gut microbiota dysbiosis, notably in the context of cirrhosis, promotes hepatic inflammation and fibrosis primarily through Toll-like receptor 4 (TLR4) mediated signaling pathways." (PMID 41245267, 2025). "Urinary Toll-like receptor-4 is increased in acute deterioration of cirrhosis with acute kidney injury compared with stable cirrhosis and controls, but because it rises with infection/inflammation, it should be interpreted alongside structural injury markers." (PMID 41301868, 2025). "Additional candidates (trefoil factor-3, glutathione-S-transferases, osteopontin, Toll-like receptor-4, and monocyte chemoattractant protein-1) come from small studies and require further validation in cirrhosis." (PMID 41301868, 2025). "TLR4 expression increases with advancing cirrhosis and promotes HCC but is relatively low in HCC compared to adjacent normal tissue." (PMID 39824843, 2025).
Cirrhosis (continued). "TLR4 mediates endotoxin‐induced tissue damage in liver failure and cirrhosis, with upregulated liver TLR4 expression and increased blood TLR4 ligands in patients with cirrhosis." (PMID 41235399, 2025). "In hepatic cirrhosis, TLR4-LPS interaction determines TNF, IL-1, IL-6 pro-inflammatory cytokines, and chemokines production." (PMID 38473721, 2024). "A further study revealed tubular injury and apoptosis with overexpression of TLR4 on epithelial tubular cells and increased urinary excretion of TLR4 in renal biopsies from patients with cirrhosis and renal dysfunction." (PMID 39194320, 2024). "Endotoxin receptors TLR2 and TLR4 are upregulated in healthy donor neutrophils after incubation with cirrhotic plasma and in neutrophils from patients with cirrhosis." (PMID 37822786, 2023). "The multivariable approach, involving TLR4 mutations, MELD, CTP, presence of HCC, patients’ age, gender and cause of cirrhosis showed that gender was the sole statistically significant factor (p = 0.0251), with a HR for females to males of 0.55." (PMID 36012696, 2022). "Genes activated in response to microbial components Tlr3 and Tlr4 followed a similar pattern, elevated during inflammation and cirrhosis stages compared to the HCC timepoint (all P < 0.01) in Mdr2 −/− livers." (PMID 33858327, 2021). "At the same time, the expression of TLR4 was lower in the PBMC of cirrhosis patients after the antibiotic treatment, indicating the systemic hyporesponsiveness of LPS to TLR4 in patients with cirrhosis." (PMID 33207562, 2020). "TLR4 expressed by activated stellate cells react to low LPS concentrations, which ensures the development of fibrosis and cirrhosis." (PMID 30658519, 2019). "Endotoxin/TLR4 signalling contributes to the development of fibrosis and progression to cirrhosis through hepatic stellate cell activation." (PMID 30658519, 2019). "Overall, hepatic expression of TLR4 is increased in chronic hepatitis and cirrhosis and is maintained in hepatocarcinoma." (PMID 31068809, 2019). "Consecutive patients with cirrhosis and ascitic fluid were distributed by TLR2 rs4696480, TLR4 rs4986790, and TLR9 rs187084 single-nucleotide polymorphisms." (PMID 28418003, 2017). "In summary, polymorphisms in TLR-2, TLR-4 and TLR-9 genes are associated with an increased bacterial antigen burden and a deficient pro-inflammatory cytokine response in patients with cirrhosis." (PMID 28418003, 2017). "TLR4 activation in HSCs is a key step in collagen production and a major mechanism for the development of fibrosis and cirrhosis." (PMID 29321784, 2017). "We evaluated the incidence of 3 well-known polymorphisms in TLR-2, TLR-4 and TLR-9 in patients with cirrhosis." (PMID 28418003, 2017). "The aim of the present study was to evaluate the incidence of relevant polymorphisms in TLR-2, TLR-4 and TLR-9, specific receptors of bacterial products which are frequently translocated from the gut in patients with cirrhosis." (PMID 28418003, 2017). "Findings derived from human and experimental studies have shown that inflammation and infection in cirrhosis lead to tubular damage and renal injury via up-regulation of renal tubular TLR4." (PMID 27359339, 2016). "The TLR4 expression levels were found to be significantly higher in HCC tissues with cirrhosis (P = 0.018), tumor size (P = 0.030), margin (P = 0.019), vascular invasion (P = 0.019), portal vein thrombosis (P = 0.014), and UICC T stage (P < 0.001)." (PMID 22938142, 2012). "Patients with cirrhosis also have a higher basal level of TLR4 expression, which is induced upon LPS stimulation and is persistently upregulated after 24 h of incubation with LPS." (PMID 20964825, 2010). "Toll-like receptor-4 expression in renal tubules and its urinary excretion increase with renal dysfunction and systemic inflammation in cirrhosis, and may become abnormal before creatinine rises." (PMID 41301868, 2025).
Cirrhosis (continued). "At the signaling level, the TLR4–NF-κB–STAT3 cascade is central to KC reconfiguration in cirrhosis." (PMID 41488615, 2025). "Moreover, TLR4 is a key factor in the progression to acute or chronic liver failure in patients with cirrhosis, and inhibition of TLR4 signaling pathways can not only reduce the degree of organ damage but improve patient prognosis." (PMID 37881635, 2023). "Furthermore, we constructed a multivariable model involving TLR4 mutations, age, gender, MELD CTP scores and cause of cirrhosis." (PMID 36012696, 2022). "Based on in vitro experiments, IGF-1 might serve as a potential therapeutic target for cirrhosis and intestinal barrier dysfunction via its inactivation of the TLR4/MyD88/NF-κB pathway." (PMID 36330225, 2022). "In a multivariable approach involving TLR4 mutations, MELD, CTP, patients’ age, gender and cause of cirrhosis, gender proved to be a statistically significant factor (p = 0.0123) with a HR for females to males of 0.28, as well as MELD (HR: 0.92, p = 0.0313) and CTP scores (HR: 1.40, p = 0.0140)." (PMID 36012696, 2022). "Therefore, as per the outcomes of the current study, the VitA‐lip‐TLR4‐shRNA treatment has the potential to prevent or reverse the fibrotic process in patients with early cirrhosis." (PMID 33336563, 2021). "We have evaluated the effect of TLR2 rs4696480, TLR4 rs4986790 and TLR9 rs187084 polymorphisms in the bacterial antigen load and the pro-inflammatory mediator levels in the blood of a consecutive series of patients with cirrhosis and AF." (PMID 28418003, 2017). "Moreover, a cirrhosis risk score consisting of SNPs in 7 genes (AP3S2, AQP2, AZIN1, DEGS1, STXBP5L, TLR4, and TRPM5) has been shown to predict fibrosis progression in HCV infected patients." (PMID 26950933, 2016). "It has been documented that the expression of TLR4 is increased in HBV-related cirrhosis and HCC." (PMID 26514586, 2015). "TLR4 regulation is altered in monocytes from patients with cirrhosis." (PMID 20964825, 2010). "TLR4 SNPs association with HCC occurrence was the primary endpoint, and associations with all-cause and liver-related mortality, as well as time durations between diagnosis of cirrhosis and HCC development or death and diagnosis of HCC and death were secondary endpoints." (PMID 36012696, 2022). "CXCR3 knockdown suppresses TLR4/MyD88, BIRC, and COL1A1 expression, inhibits proliferation and migration, and promotes apoptosis, thereby attenuating cirrhosis-to-carcinoma transition." (PMID 41258710, 2026). "Endotoxin‐driven TLR4 activation mediates TGF‐beta signal transduction and HSC activation, thus constituting an important mechanism of advanced cirrhosis." (PMID 41235399, 2025). "SIBO is associated with the increased expression of toll-like receptor-4 (TLR4) and secretion of IL-8, which influence the inflammatory pathways involved in the pathogenesis of MASLD and cirrhosis." (PMID 40444006, 2025). "Toll-like receptor 4 and miRNA-15b-5p gene expression levels were significantly higher in the HCC group than in the HCV, cirrhosis, and control groups." (PMID 39844891, 2025). "The expression of CD32, TLR4, and CXCR4 was increased in cirrhosis, whereas the expression of IFNAR, CD206, CCR5, and CCR7 was reduced." (PMID 37004869, 2023). "Toll-like receptor (TLR-4) appears to have a role in hepatocarcinogenesis, as TLR-4 expression increased as chronic hepatitis progressed to cirrhosis and then to HCC." (PMID 35867269, 2023). "And lastly, it has been reported that in rats with cirrhosis, BCAAs can reduce the protein expression of LBP and TLR4, which are the driving factors leading to immune cell exhaustion." (PMID 37252239, 2023). "When comparing advanced cirrhosis with HCC time points, a further reduction in several proinflammatory cytokines including Tlr4 and IL-1β was seen (P = 0.0037 and P = 0.0032, respectively)." (PMID 33858327, 2021).
Cirrhosis (continued). "Our study supports the role of bacterial translocation, indicated by the significant increase of hepatic TLR-4 expression in the BDL model 7 d after IM and significantly higher levels of endotoxin in the cirrhosis models." (PMID 34489738, 2021). "It is worth noting that within this global immunosuppressed intrahepatic environment, a further reduction in key intrahepatic genes activated in response to microbial components and LPS, including Tlr4 and IL-1β was seen in HCC compared to advanced cirrhosis." (PMID 33858327, 2021). "Both protein expression levels of TLR4 and SOX2 were significantly elevated in relapsed HCC samples when compared with the cirrhosis samples and unrelapsed HCC samples." (PMID 30957973, 2019). "We detected the expressions of TLR4 and SOX2 by immunohistochemistry in HCC primary lesion samples and cirrhosis samples." (PMID 30957973, 2019). "Therefore, our study aimed to assess the potential role of miR-15b-5p and Toll-like receptor 4 as biomarkers for the diagnosis of HCC in the sera of Egyptian patients with HCV and/or cirrhosis." (PMID 39844891, 2025). "More precisely, the median time between cirrhosis and HCC diagnoses was 47 months (range 11–160) for patients with TLR4 mutations and 46 (range 1–204) for those without." (PMID 36012696, 2022). "Single studies assessed the potential role of other novel biomarkers including TFF-3, GST, OPN, MCP-1, and TLR4; however, due to the lack of data, further evaluation of their utility in differential diagnosis of acute renal dysfunction among patients with cirrhosis." (PMID 38139297, 2023). "Preventing hepatic MF activation by targeting the LPS–TLR4 axis may thus represent a valid therapeutic strategy for CLD, especially since pharmacological inhibition of TLR4 has already been shown to ameliorate liver injury and inflammation in experimental fibrosis/cirrhosis." (PMID 34831182, 2021). "Moreover, our study lacks evaluation of histopathological findings between patients with and without TLR4 SNPs; this is due to the fact that HCC diagnosis can be established with typical radiological findings in patients with cirrhosis; thus, only a handful of patients underwent liver biopsy." (PMID 36012696, 2022).
coronary artery disease (56 papers, 2009 to 2025). "Among symptomatic men with coronary artery disease, this TLR4 variant modifies the efficacy of pravastatin in preventing cardiovascular events." (PMID 32378144, 2021). "For example, coronary artery disease is associated with increased monocyte TLR4 expression and an inflammatory phenotype." (PMID 29649324, 2018). "TLR2 and TLR4 are expressed by macrophages, neutrophils, and dendritic cells and have been implicated in the development of coronary artery disease (CAD) through activation of NF-κB pathways." (PMID 27795867, 2016). "We demonstrate an association between the TLR4 SNP rs4986790 genotype and age-dependant blood pressure increase in patients with coronary artery disease." (PMID 26015800, 2015). "We demonstrate an association between the TLR4 SNP rs4986790 genotype and age-dependant blood pressure increase in large cohort of patients with coronary artery disease." (PMID 26015800, 2015). "TLR4 may serve as a potential clinical biomarker for cardiovascular risk in patients with coronary artery disease." (PMID 39453113, 2024). "Interestingly, the overexpression of TLR3 and TLR4 has been implicated in the severity of coronary artery disease." (PMID 37958848, 2023). "Polymorphisms in the TLR4 gene may alter TLR4 expression and affect the extent and severity of coronary artery disease (CAD)." (PMID 28002812, 2017). "Interestingly, TLR4 dependent macrophage signaling is associated with coronary arterial disease and a TLR4 agonist has been shown to stimulate hepcidin expression." (PMID 28881695, 2017). "Moreover, TLR4 dependent macrophage signaling is associated with coronary arterial disease." (PMID 28061462, 2017). "The activation of TLR4 in vascular cells initiated the vascular inflammatory response and promoted coronary artery disease." (PMID 35425840, 2022). "Previous studies have reported that S100A12 was an important inflammatory marker in coronary heart disease, therefore, TLR4 and TREM1 were further studied." (PMID 34221733, 2021). "The presence of TLR4 in unstable plaques suggests that it is a major factor of coronary artery disease progression." (PMID 30225265, 2018). "Functional polymorphisms of TLR-4, Asp299Gly and Thr399Ile, CD14 promoter area C260T polymorphism and plasma levels of soluble CD14 are studied in subjects with Coronary Artery Disease (CAD)." (PMID 29367560, 2016). "TLR4 is elevated at both the mRNA and protein level in mononuclear cells of patients with coronary artery disease." (PMID 26030867, 2015). "TLR4 is activated in peripheral monocytes and heart tissue obtained from patients with ischemic heart disease and reduced left ventricular function." (PMID 26030867, 2015). "TLR4 expression levels are higher on monocytes from patients with peripheral or coronary artery disease than in healthy individuals." (PMID 24945347, 2014). "Another study suggested that atorvastatin downregulated TLR4 signal via let-7i expression in patients with coronary heart disease, possibly contributing to the benefit effects of atorvastatin on this disorder." (PMID 23437218, 2013). "By demonstrating its efficacy in ameliorating dysfunction, inflammation, and fibrosis post-AMI via targeted inhibition of the TLR4/MyD88/NF-κB pathway, this study validates its traditional use and offers a compelling candidate for targeted treatment of ischemic heart disease." (PMID 41155364, 2025). "Thus, the contradictory observations regarding TLR4 in ischemic heart disease are most likely related to its different ligands (e.g., HSP27 and Hsp60), which are dispersed throughout ischemic hearts, where they interact with TLR4 and cause diverse outcomes." (PMID 31817787, 2019). "It is logical to consider that TLR4-mediated signaling might be a potential target for intervention in the initiation and progression of coronary heart disease (CHD)." (PMID 28793055, 2017).